PER3 (period circadian regulator 3)
Diseases named in the same sentence as PER3 in open-access papers (continued):
Sharing a sentence is not in itself a finding about the gene and the disease.
Anxiety (11 papers, 2016 to 2025). Intense feelings of nervousness, tension, or panic often arise in response to interpersonal stresses. "In males, the CRY1_CC/PER3-A_GG combination was directly associated with severe anxiety, and ZBTB20 variants occurred in risk combinations with CRY2_AG and PER3-B_GG." (PMID 38102312, 2023). "In males, CRY1_CC/PER3-A_GG was a risk factor for severe anxiety and PER3-B_GG/ZBTB20_TT was a risk factor for mild anxiety." (PMID 38102312, 2023). "PER3-A_CC/ZBTB20_TT was associated with a near five-fold decrease in odds of moderate anxiety (OR 0.02(0.0011–0.49) adj." (PMID 38102312, 2023). "PER3-A_CG/ZBTB20_TT was associated with a near 40-fold reduction in odds of severe anxiety (OR 0.02(0.0011–0.57) adj." (PMID 38102312, 2023). "CRY1_GG/PER3-A_GG was associated with a 2.5-fold increase in odds of severe anxiety (OR 2.5(1.32–4.86) adj." (PMID 38102312, 2023). "PER3-B_GG/ZBTB20_TT was associated with a ~ sevenfold increase in odds of mild anxiety (OR 7.3(1.47–36.60) adj." (PMID 38102312, 2023). "ZBTB20 was associated with increased anxiety risk in combinations with CRY2_AG and CRY2_GG and was associated with decreased anxiety risk in combinations with PER3-A_CG and PER3-A_CC." (PMID 38102312, 2023). "CRY1_CC/PER3-A_GG was associated with nearly three times the odds of severe anxiety (OR 2.8(1.22–6.49) adj." (PMID 38102312, 2023). "It is well known that PER3 is a circadian gene that is in a robust association with diurnal preference, mood, and anxiety levels." (PMID 33920292, 2021). "Our sleep duration x genotype interaction analyses showed that, relative to longer allele carriers, PER3(4/4) genotypes were at greater risk for transient psychological effects (mood and state anxiety) when they reported reduced sleep durations." (PMID 27103936, 2016). "Interestingly, we found that the association between CRY1_GG/PER3-A_GG and severe anxiety in females was partially mediated by extreme evening type behavior." (PMID 38102312, 2023). "We also observed that CRY1_GG/PER3-A_GG was associated with severe anxiety in females." (PMID 38102312, 2023). "Other scholars also identified PER3 mutations associated with chronotype and anxiety." (PMID 36033630, 2022). "For both sexes, severe anxiety is associated with a 120-fold increase in odds for individuals with CRY2_AG(rs1083852)/ZBTB20_TT(rs1394593) genotypes and is associated with a near 40-fold reduction in odds for individuals with PER3-A_CG(rs228697)/ZBTB20_TT(rs1394593) genotypes." (PMID 38102312, 2023). "Finally, molecular chronotype and circadian misalignment are strong predictors of anxiety symptoms, indicating that indirect effects of clock gene variants, particularly in the PER3 gene, may also play a role in modulating anxiety symptoms." (PMID 35365695, 2022). "The CRY1_GG/PER3-A_GG genotype in females exhibited effects partially mediated by extreme evening-type behavior, suggesting that circadian effects on anxiety can be both direct and/or mediated by chronotype." (PMID 38102312, 2023). "In females, the CRY2/ZBTB20 genotype combination showed a > 200-fold increase in odds of anxiety and PER3/ZBTB20 and CRY1 /PER3-A genotype combinations also appeared as female risk factors." (PMID 38102312, 2023). "All other variants (PER2, PER3 VNTR, PER3A, CLOCK3111, CRY1, and CRY2 SNPs) were directly associated with anxiety symptoms following bootstrap analysis." (PMID 35365695, 2022). "Genetic circadian disturbances, specifically variants in the circadian genes PER3 and ARNTL2, have been linked with anxiety." (PMID 35126036, 2021). "Hippocampal expression of per3 has been tightly correlated to anxiety-related behaviors and modulation by stress-exposure proposes an important function of forebrain per3 in the regulation of emotional states." (PMID 26679264, 2016). "Also, PER3-A_CG/ZBTB20_TT and PER3-A_CC/ZBTB20_TT were protective for mild and moderate anxiety in females." (PMID 38102312, 2023).
Anxiety (continued). "In these analyses, the top twelve rules with the strongest effects on anxiety symptoms included clinical features and two, three, and four-way gene combinations as strong predictors of human anxiety; only one factor represented a single gene (the PER3 VNTR_5,5 genotype; Suppl." (PMID 35365695, 2022). "Women with the PER3 genotype have fewer depressive symptoms and more anxiety symptoms." (PMID 36033630, 2022). "Here we show that two PER3 mutations, a variable number tandem repeat (VNTR) allele and a single-nucleotide polymorphism (SNP), are associated with diurnal preference and higher Trait-Anxiety scores, supporting a role for PER3 in mood modulation." (PMID 28860482, 2017). "For example, polymorphisms in BMAL and PER3 were found to be significantly associated with bipolar disorder, CRY1 polymorphisms has been associated with major depression, and a mutation in the CLOCK gene results in decreased anxiety and mania." (PMID 27103936, 2016). "There was not a significant main effect for PER3 genotype on state anxiety scores (p > 0.05), but there was a significant interaction between PER3 genotype and sleep duration on state anxiety scores F = 4.07, p = 0.04." (PMID 27103936, 2016).
mood disorder (10 papers, 2010 to 2025). A cognitive disorder a disturbance in which the person's mood is hypothesized to be the main underlying feature. "Polymorphisms in a circadian clock-related gene, PER3, are associated with behavioral phenotypes (extreme diurnal preference in arousal and activity) and sleep/mood disorders, including seasonal affective disorder (SAD)." (PMID 28860482, 2017). "Our results indicate that additive effects of risk alleles in the PER3 gene may influence mood disorders and sleep quality." (PMID 41009992, 2025). "Associations between PER3 genotypes and mood disorders have robust support in the literature." (PMID 28860482, 2017). "Variants in genes including PER3, CLOCK, and BMAL1 influence not only circadian phase preference but also cognitive performance patterns, mood disorder susceptibility, and drug metabolism." (PMID 41226802, 2025). "We also utilize a comprehensive circadian clock model to explore and evaluate potential mechanisms connecting PER3 to human mood disorders." (PMID 28860482, 2017). "We hypothesise that if the circadian system is part of the pathophysiology of mood disorders in dLAN, Per3−/− mice would exhibit an altered time of onset of anhedonia-like behaviour than wild-type (WT) mice do." (PMID 28071711, 2017). "Previous studies have demonstrated important associations of clock genes with sleep and mood disorders, as for example between PER2 variants and familial ASPS, between PER3 variants and diurnal preference and DSPS, and between CLOCK and mood disorders and human diurnal preference." (PMID 20174623, 2010).
sleep disorder (10 papers, 2015 to 2025). A change from the patient's baseline sleeping pattern, in the hours slept and/or an alteration/dysfunction in the stages of sleep. "Our study reports multiple associations of PER3 SNPs with mood and sleep disorders in university students." (PMID 41009992, 2025). "As an important gene regulating circadian rhythms, variants in the PER3 gene are predominantly associated with the occurrence of sleep disorders." (PMID 39108697, 2024). "In our AD patients, the PER3_rs228697 variant was associated with symptoms of circadian rhythm disorder according to the sleeping disorders questionnaire." (PMID 36901420, 2023). "Mutations in the period gene, PER3, are implicated in sleep disorders associated with shifts in circadian rhythms and are thought to increase susceptibility to MDD." (PMID 35422091, 2022). "Polymorphisms in the PER3 gene have been associated with several human disease phenotypes, including sleep disorders and cancer." (PMID 34508103, 2021). "In humans, CLOCK gene SNPs are connected to body weight, metabolic syndrome risk, and insomnia, while PER2 and PER3 gene SNPs are linked to sleep disturbances." (PMID 32050674, 2020). "Previous studies have linked single PER3 variants with both mood and sleep disorders, suggesting that the PER3 gene may play a role in modulating mental health and sleep quality." (PMID 41009992, 2025). "In addition, we investigate whether specific PER3 SNP haplotypes increase or decrease the risk of mood or sleep disorders in young adults, indicating additive effects of multiple variants within this gene influence mood and sleep regulation pathways." (PMID 41009992, 2025). "BPSD in the patients’ group were evaluated with NPI, PHQ-9 and the sleeping disorders questionnaire; then, they were analyzed for associations with the genetic variants of PER2, PER3, OX2R and APOE." (PMID 36901420, 2023). "In addition, PER3 and other circadian clock variants display different allele frequencies across diverse populations, suggesting that particular variants may influence mood and sleep disorders in some populations but not others." (PMID 41009992, 2025).
metabolic syndrome (8 papers, 2017 to 2024). A cluster of metabolic risk factors for CARDIOVASCULAR DISEASES and TYPE 2 DIABETES MELLITUS. "In the present study, hypermethylation of the per3 gene was observed at the end of the BWRP only in the group with metabolic syndrome." (PMID 36497566, 2022). "Post-BWRP changes in the methylation levels of clock, cry2 and per2 genes occurred in the entire population, together with hypermethylation of clock and per3 genes in males and in subjects with metabolic syndrome." (PMID 36497566, 2022). "Among the cardiometabolic outcomes that did not change in obese adolescents without metabolic syndrome, we might invoke REE, FFM and ACTH-3PM as potential causative factors of the missing post-BWRP hypermethylation of the per3 gene in this group." (PMID 36497566, 2022). "Importantly, the BWRP-induced hypermethylation of the per3 gene might be interpreted as a negative outcome due to the post-BWRP decrease in REE and FFM in the group with metabolic syndrome, which would clinically indicate energy storage and muscle protein waste." (PMID 36497566, 2022).
type 2 diabetes (8 papers, 2016 to 2025). "Impairment of the circadian clock genes such as CLOCK, BMAL1, cryptochrome (CRY1 and CRY2), and period (PER1, PER2, and PER3) contributes to the decrease in glucose tolerance, defective β-cell function, and the development of type 2 diabetes." (PMID 28352282, 2017). "Although it is not directly related to those SNPs above, PER3 length polymorphism in its exon 18 has been reported in patients with type 2 diabetes." (PMID 37768516, 2023). "On the other hand, mechanisms that impair the circadian clock genes, such as circadian locomotor output cycles kaput (CLOCK), brain and muscle Arnt-like protein 1 (BMAL1), and period genes (PER1, PER2, and PER3), contribute to defective beta-cell function and development of type 2 diabetes." (PMID 28352282, 2017). "In addition, the transcript level of PER3 was reduced in type 2 diabetes patients." (PMID 37768516, 2023). "Indeed, when mRNA expression levels were compared between cultured human islets from deceased donors, Per2, Per3, and Cry2 were under-expressed in type 2 diabetes mellitus (T2DM) patients compared to healthy donors, alluding that metabolic function correlates with robust clock rhythms." (PMID 31555652, 2019). "In a human study, leucocytes sampled from subjects with type 2 diabetes expressed significantly lower transcript levels of BMAL1, PER1, and PER3 compared with leucocytes from normal controls; moreover, transcript expression was inversely correlated with HbA1c levels." (PMID 28352282, 2017).
glioma (7 papers, 2022 to 2025). A benign or malignant brain and spinal cord tumor that arises from glial cells (astrocytes, oligodendrocytes, ependymal cells). "The expression level of Per3 is reduced in the case of gliomas, which is linked with higher mortality." (PMID 40495887, 2025). "This study analyzed the diagnostic value of PER3 in GBM by selecting two molecular pathology indicators of GBM from the Glioma Diagnostic and Treatment Guidelines and analyzing the ROC curves together with PER3 as a diagnostic factor." (PMID 39771050, 2024). "It is noteworthy that the expression of PER1, PER2, PER3 is also downregulated in high-grade gliomas and associated with increased proliferation and survival of glioma cells." (PMID 36796229, 2023). "While BMAL1 and CLOCK are vital for GSC survival, PER1, PER2, and PER3 are downregulated in high-grade gliomas." (PMID 39413708, 2024). "PCR results indicate that the expression of circadian rhythm factor PER3 was significantly reduced in the brains of zebrafish in the exposed group, and circadian dysregulation had a certain promoting effect on the development of glioma." (PMID 39771050, 2024). "It was demonstrated that PER3 is an effective early diagnostic marker, which is of great significance in the diagnosis and clinical prognosis of glioma, and that DEHP exposure can lead to a significant reduction in PER3 expression in zebrafish brain tissue." (PMID 39771050, 2024). "The differential expression of CCGs in glioma grading confirmed that cluster I genes (ARNRL, NPAS2, and TIMELESS) and CRY1, with cluster II genes (CRY2, DBP, NR1D1, NR1D2, PER2, PER3, and RORA) showed significantly opposite expression trends in brain tissues." (PMID 35832846, 2022). "Besides, the expression of eight CCGs (CRY2, DBP, NR1D1, NR1D2, PER2, PER3, RORA, and TIMELESS) was negatively regulated by methylation and positively regulated by CNV in glioma, which is consisting with previous studies that DNA methylation and CNV can promote abnormal gene expression." (PMID 35832846, 2022).
lung carcinoma (7 papers, 2018 to 2024). "Previous studies showed that circadian rhythm-related factors such as the ARNTL, CLOCK, RORA, RORB, CRY1, CRY2, and PER3 genes were associated with a higher risk of lung cancer." (PMID 36385012, 2022). "PER3 has been confirmed to affect the susceptibility and prognosis of lung cancer through expression changes, methylation, and single nucleotide polymorphisms (SNPs)." (PMID 34285836, 2021). "Moreover, lower mRNA of PER1, PER2 and PER3 are linked to poor overall survival rates in lung cancer patients, indicating that these genes are prognostic markers." (PMID 34162762, 2021). "Furthermore, we used the CCLE to analyze mRNA expression levels of PER1, PER2, PER3, CRY1, and CRY2 in lung cancer cell lines in current lung cancer research." (PMID 36385012, 2022). "In contrast, the correlations between PER3, TEF, HLF and DBP are not altered in lung cancer." (PMID 39004631, 2024).
colon cancer (5 papers, 2020 to 2024). "In other solid tumors, low levels of PER3 are identified in colon cancers vs. normal tissues, which are associated with colon cancer incidence and development." (PMID 33816508, 2021). "Thus, novel agents that could activate PER3 to suppress cancer stemness could emerge as a promising strategy to reverse chemoresistance in colon cancer." (PMID 33114496, 2020).
asthma (4 papers, 2016 to 2023). "NR1D2 and PER3 have been associated with asthma in mice through bioinformatics analysis of genes and pathways." (PMID 28886691, 2017). "The molecular clock in blood cells in asthma is altered; PER3 is significantly more rhythmic in asthma compared to healthy controls." (PMID 37404842, 2023). "After adjusting for false discovery rate (FDR), PER3 remained significantly circadian rhythmic in asthma, compared to health (FDR=0.01)." (PMID 37404842, 2023). "In our analysis, among the seven core clock genes, we found only PER2 and PER3 have a slightly but significantly higher expression in the blood samples from asthma patients." (PMID 37108640, 2023). "PER2 (adjusted p = 0.003) and PER3 (adjusted p = 0.002) expressions were statistically higher in the blood samples of asthma patients." (PMID 37108640, 2023). "Overall, there was more variation in the expression of PER2, PER3 and NR1D1 at later time points (16:00 h and 22:00 h) compared to morning time points (04:00 h and 10:00 h) in asthma compared to health." (PMID 37404842, 2023). "There was a significant increase in the expression of PER3 at 22:00 h (p<0.05) and PER2 at 04:00 h (p<0.05) in asthma compared to healthy samples." (PMID 37404842, 2023). "In line with our results, PER2 and PER3 were increased, most noticeably when collected between 4 pm and 9 pm for PER2 and between 9 am and 9 pm for PER3, in peripheral blood mononuclear cells from asthma patients (unpublished results, scientific meeting abstracts)." (PMID 37108640, 2023). "Both PER3 and NR1D1 were significantly rhythmic in those with asthma (p<0.01 and p<0.05, respectively), but not in healthy people." (PMID 37404842, 2023).
hepatocellular carcinoma (4 papers, 2015 to 2022). A malignant tumor that arises from hepatocytes. "Another recent study used methylation arrays and stringent selection criteria to screen >14,000 genes to identify putative tumor suppressors associated with human hepatocellular carcinoma; PER3 was one of only three candidate tumor suppressor genes identified." (PMID 25501848, 2015). "For instance, a synonymous SNP in PER3 gene, rs2640908, has been found to be correlated with prognosis of hepatocellular carcinoma(HCC) patients with TACE treatment." (PMID 26927666, 2016).
insomnia (4 papers, 2018 to 2022). A sleep disorder characterized by difficulty in falling asleep and/or remaining asleep. "In human populations, PER3 variants were associated with insomnia severity in alcohol-dependent patients." (PMID 30319684, 2018).
Insulin resistance (4 papers, 2021 to 2025). Increased resistance towards insulin, that is, diminished effectiveness of insulin in reducing blood glucose levels. "From association rule mining results, we could find that homozygous minor allele contents in a circadian gene such as PER3 may predispose individuals to be more prone to insulin resistance although additional evidence from further research is necessary." (PMID 37768516, 2023). "Homozygous minor alleles of genes such as PER3 and MAC of the circadian genes may predispose individuals to insulin resistance." (PMID 37768516, 2023). "Further research may be necessary to clarify the relationship of the PER3 variations to the development of insulin resistance in humans." (PMID 37768516, 2023). "Additionally, the expression levels of PER1, PER3, and BMAL1 molecular-clock genes in leukocytes obtained from patients with T2D was seen inversely correlated with hemoglobin A1C (HbA1c) levels, indicating an association between insulin resistance and T2D." (PMID 37475884, 2023). "In summary, we have identified disrupted circadian rhythms in key genes (PER3, ARNTL, TSSK6, HOXB5) in skeletal muscle cells from individuals with T2D, advancing current understanding of how intrinsic timekeeping mechanisms contribute to insulin resistance." (PMID 40495716, 2025).
astroblastoma (3 papers, 2024 to 2025).